ROBO2 (roundabout guidance receptor 2)
Description:
Receptor for SLIT2, and probably SLIT1, which are thought to act as molecular guidance cue in cellular migration, including axonal navigation at the ventral midline of the neural tube and projection of axons to different regions during neuronal development.
Synonyms: KIAA1568; SAX3
Tractability: Antibody: its Gene Ontology location is reachable by antibodies, with high confidence; UniProt predicts a signal peptide or a membrane-spanning region; the Human Protein Atlas places it where antibodies can reach. PROTAC: its protein half-life has been measured.
Gene: Protein-coding gene on chromosome 3 (75,906,695 to 77,649,964, forward strand). Ensembl gene ENSG00000185008.
Subcellular location: Membrane
Subcellular location (Human Protein Atlas): Plasma membrane; Vesicles
Pathways (Reactome):
Developmental Biology: Formation of the ureteric bud; ROBO receptors bind AKAP5; Regulation of commissural axon pathfinding by SLIT and ROBO; Regulation of cortical dendrite branching; Regulation of expression of SLITs and ROBOs; Signaling by ROBO receptors
Gene Ontology:
Molecular function: identical protein binding; protein binding; axon guidance receptor activity
Biological process: apoptotic process involved in luteolysis; brain development; cellular response to hormone stimulus; homophilic cell-cell adhesion; negative regulation of negative chemotaxis; positive regulation of axonogenesis; ureteric bud development; aorta development; aortic valve morphogenesis; axon guidance; axon midline choice point recognition; cell-cell adhesion; central nervous system development; endocardial cushion formation; heart induction; metanephros development; negative regulation of synapse assembly; olfactory bulb interneuron development; outflow tract septum morphogenesis; positive regulation of Notch signaling pathway; pulmonary valve morphogenesis; retinal ganglion cell axon guidance; ventricular septum morphogenesis; tube development
Cellular component: cell surface; extracellular exosome; axolemma; plasma membrane; membrane
Genetic constraint (gnomAD): Loss-of-function variants: 51 observed, 156.24 expected, observed/expected ratio (o/e) 0.33, 90% interval 0.26 to 0.41. The upper end of that interval is the gene's LOEUF score, 0.41, which puts it in group 1 of 6, group 1 being the genes least tolerant of losing a copy. Missense variants: 1,526 observed, 1,742.5 expected, observed/expected ratio (o/e) 0.88, 90% interval 0.84 to 0.91. Synonymous variants: 648 observed, 622.93 expected, observed/expected ratio (o/e) 1.04, 90% interval 0.98 to 1.11.
Homologues: Orthologues: guinea pig ROBO2 (97% identical), mouse Robo2 (94% identical), rat Robo2 (94% identical), chimpanzee ROBO2 (94% identical), macaque ROBO2 (92% identical), pig ROBO2 (91% identical), rabbit ROBO2 (91% identical), tropical clawed frog robo2 (84% identical), zebrafish robo2 (68% identical). Paralogues in human: ROBO1 (54% identical), ROBO3 (42% identical), SDK2 (19% identical), NEO1 (18% identical), SDK1 (17% identical), DCC (17% identical), IGDCC4 (17% identical), NRCAM (16% identical), PRTG (16% identical), CNTN4 (16% identical), HMCN2 (16% identical), L1CAM (16% identical), and 24 more.
Diseases named in the same sentence as ROBO2 in open-access papers:
ROBO2 is named in the same sentence as 107 diseases in open-access papers, as found by Europe PMC text mining. Sharing a sentence is not in itself a finding about the gene and the disease. The quoted sentences say what the papers report.
autism (10 papers, 2011 to 2025). Persistent deficits in social interaction and communication and interaction as well as a markedly restricted repertoire of activity and interest as well as repetitive patterns of behavior. "In turn, the rest-induced E3 ubiquitin ligase MYCBP2 reportedly cooperates with ROBO2 in the olfactory system development in mice and is associated with neurodevelopmental problems and autism in humans." (PMID 40725218, 2025). "ROBO2 has been further associated with vocabulary growth, autism, and dyslexia and is involved in the development of neural circuits related to vocal learning in birds." (PMID 28720580, 2017). "It is of particular interest that a loss of ROBO2/Slit function affects development of the serotonergic and dopaminergic systems, both of which are implicated in the pathophysiology of autism." (PMID 21859478, 2011). "Robo1 and Robo2 has also been shown to be deficient in some cases of autism, suggesting that this pathway may be a possible mechanism by which HS deficiency could cause autism." (PMID 27089953, 2016). "Together, the coordinated downregulation of Nrp1, Nrp2, Robo2, and Dpysl3 suggests potential impairment in axon-guidance signaling cascades in autism." (PMID 41150532, 2025). "Among them, ROBO2 is involved in thalamocortical axons development and has been related to autism and asocial behavior, but also to dyslexia and expressive vocabulary growth in the normal population." (PMID 26060509, 2015). "The results provide the first evidence, to our knowledge, of reduced mRNA and protein levels of axon-guidance receptors, including those of PLXNA4 and ROBO2, in the ACC of people with autism; this region has previously been implicated in the pathophysiology of autism." (PMID 21859478, 2011). "In this study, we found decreased expression of axon-guidance proteins such as PLXNA4 and ROBO2 in the brains of people with autism, and suggest that dysfunctional axon-guidance protein expression may play an important role in the pathophysiology of autism." (PMID 21859478, 2011). "It has been reported that aberrant axon-guidance protein expression was observed in the brains of people with autism, including the decreased expression of PLXNA4 and ROBO2." (PMID 33679870, 2020). "Real-time RT-PCR revealed that the relative expression levels of EFNB3, PLXNA4A and ROBO2, compared, with all three housekeeping genes were significantly lower in the ACC of people with autism than in the ACC of controls." (PMID 21859478, 2011).
dyslexia (8 papers, 2014 to 2024). A learning disorder characterized by an impairment in processing written words. "ROBO1 has well-established roles in brain development, and has been implicated in dyslexia as well as phonological short-term memory, while its homologue ROBO2 has been linked with expressive vocabulary during early language acquisition." (PMID 36794006, 2020). "ROBO1 and ROBO2 genes are mapped at the dyslexia susceptibility loci DYX5, which is located on chromosome 3 (3p12-q13)." (PMID 33425915, 2020). "In this context, a decrease in ROBO2 expression can cause a deficit in neurological development, causing various disorders, such as intellectual disability, schizophrenia, epilepsy, learning disabilities, Parkinson’s disease, and dyslexia, as well as affecting other fundamental biological processes." (PMID 38612763, 2024). "Here, the authors show that a genetic variant near the ROBO2 gene is associated with early language acquisition in the general population and highlight a potential genetic link between language-related common genetic variation and a linkage region for dyslexia, speech-sound disorder and reading." (PMID 25226531, 2014). "Interestingly, another member of the roundabout gene family, roundabout guidance receptor 2 (ROBO2), is located near ROBO1 in a head-to-head orientation within the dyslexia susceptibility haplotype." (PMID 26877820, 2016).
pancreatic cancer (8 papers, 2016 to 2025). "Robo2 suppresses stromal activation in pancreatic cancer through divergent mechanisms during development." (PMID 40508075, 2025). "So far, researchers have mainly studied the role of Robo2 in pancreatic cancer and liver fibrosis." (PMID 38297025, 2024). "Similarly, ROBO2 was shown to act as a tumor suppressor in pancreatic cancer, while being simultaneously a marker of poor prognosis in inflammatory BC." (PMID 36057630, 2022). "Robo3, the inhibitor of Robo2, activates the WNT/β-catenin pathway, thus promoting pancreatic cancer growth and invasion." (PMID 32670371, 2020). "Roundabout guidance receptor 2 (Robo2) is closely related to malignant tumors such as pancreatic cancer and liver fibrosis, but there is no relevant research on the role of Robo2 in HCC." (PMID 38297025, 2024).
colorectal cancer (6 papers, 2015 to 2023). A primary or metastatic malignant neoplasm that affects the colon or rectum. "Down regulation and mutations in ROBO2 have been reported in prostate, gastric and colorectal cancers; while LAMA2 down regulation has been reported in drug-resistant ovarian cancer cell lines." (PMID 26620706, 2015). "A similar model with co-occurrences of mutation and loss of expression of ROBO1 and ROBO2 has been reported in colorectal cancers, supporting our speculation." (PMID 26608094, 2015). "ROBO2 has been identified as a candidate tumor suppressor, and the alteration of its expression might play a role in malignant tumors of digestive tract including gastric and colorectal cancers." (PMID 31598423, 2019). "Other pathways identified were Beta‐catenin‐dependent transcription regulation in colorectal cancer; Development_ROBO2, ROBO3, and ROBO4 signaling pathways, Notch signaling in oligodendrocyte precursor cell differentiation in multiple sclerosis and Signal transduction_mTORC1 upstream signaling." (PMID 36329628, 2023).
liver fibrosis (6 papers, 2019 to 2024). "It has been found that ROBO2 membrane receptor can promote the progression of liver fibrosis by activating the PI3K-AKT pathway upon binding to the ligand SLIT2." (PMID 39113997, 2024). "Our research group previously also substantiated that sTREM-1/Robo2 strengthened HSCs activation and the occurrence of hepatic fibrosis through PI3K/Akt and Smad2/3 signaling pathways." (PMID 38297025, 2024). "Former studies found that liver fibrosis was mediated by activating hepatic stellate cells through the Slit2/Robo1 and Slit2/Robo2 signal pathway." (PMID 35111704, 2021). "While none of these proteins has been well characterized in lung fibrosis, it has been shown that ROBO2 is overexpressed in a mouse model of toxin-induced liver fibrosis, and that the interaction between ROBO2 and its ligand promotes fibrogenic activity within stellate cells." (PMID 35066606, 2022). "In addition, Zeng found that Slit2/Robo2 mediates the development of liver fibrosis and regulates the biological behaviour of HSCs by activating PI3K/Akt signalling pathway in a model of thioacetamide‐induced mouse liver fibrosis." (PMID 34750987, 2021). "sTREM‐1 has synergistic effect with CCl4 on liver fibrosis via Robo2‐Smad2/3 and PI3K/Akt pathway, knocking down Robo2 or inhibiting Smad2/3 or PI3K/Akt significantly blocked the sTREM‐1‐induced HSC activation and liver fibrosis." (PMID 34750987, 2021). "Previous studies point out that Robo2 regulates both PI3K/Akt and Smad2/3 pathways in liver fibrosis." (PMID 34750987, 2021). "Our research proved that sTREM‐1 bound to the HSC membrane receptor Robo2 activating the downstream Smad2/3 and PI3K/Akt signalling pathways and clarified its role and mechanism for promoting liver fibrosis." (PMID 34750987, 2021). "In conclusion, this study innovatively used sTREM‐1 as a novel ligand for membrane receptor Robo2 to explore its effects on HSC activation and liver fibrosis, breaking through the limitation of previous studies that only focused on the functions of TREM‐1 receptor." (PMID 34750987, 2021). "Moreover, we further verified the role of membrane receptor Robo2 and its downstream PI3K/Akt and Smad2/3 signalling pathways in sTREM‐1‐related liver fibrosis in vivo." (PMID 34750987, 2021). "In conclusion, sTREM‐1 acts as a new ligand of Robo2; the binding of sTREM‐1 to Robo2 initiates the activation of the downstream Smad2/3 and PI3K/Akt signalling pathways, thereby promoting HSC activation and liver fibrosis." (PMID 34750987, 2021).
schizophrenia (6 papers, 2011 to 2026). A major psychotic disorder characterized by abnormalities in the perception or expression of reality. "ROBO2 was also implicated in schizophrenia, and psychopathic tendencies, although a subsequent study replicated the emotionally reactive, impulsive aspects of conduct disorder, but not the concurrent risk for psychopathy." (PMID 36253440, 2023). "Other genes in this FOXP2 gene cluster include NRG3, ERBB4, DLX1, ROBO2, and ROBO2, all are susceptibility gene in schizophrenia and is related to development." (PMID 33658499, 2021).
myelodysplastic syndrome (4 papers, 2015 to 2025). A clonal hematopoietic disorder characterized by dysplasia and ineffective hematopoiesis in one or more of the hematopoietic cell lines. "Similarly, PAT5 and PAT9, patients with mutations of ROBO2—a gene associated with progression of myelodysplastic syndrome to AML and recently reported as mutated in pediatric ALL —present the ETP phenotype." (PMID 33225950, 2020). "Based on the morphology, immunology, cytogenetics, and molecular biology of bone marrow cells, the patient was diagnosed with myelodysplastic syndrome (MDS, +8, -7, IPSS-R 5.5 points, JAK2, ROBO2, and CROCC mutations)." (PMID 40881710, 2025). "Additionally, using whole-exome and targeted sequencing in 209 patients with myelodysplastic syndrome (MDS) found ROBO1 and ROBO2 mutations in 26 (12.4%) patients." (PMID 30820596, 2019).
ovarian carcinoma (4 papers, 2011 to 2022). A malignant neoplasm originating from the surface ovarian epithelium. "Downregulation of ROBO2 expression was observed in the poorly differentiated SKOV-3 ovarian cancer cell line in comparison to the more differentiated PEO-14 ovarian cancer cell line." (PMID 35628654, 2022). "Decreased expression of ROBO2 was observed in primary cultures of ovarian cancer epithelial cells, compared to normal OSE, and in poorly differentiated SKOV-3 cells, compared to the more differentiated PEO-14 cells." (PMID 35008952, 2022). "We observed the downregulation of ROBO2 in the TOP-resistant A2780TR2 cell line, and previously we also observed the downregulation of ROBO2 in two CIS-resistant ovarian cancer cell lines, which suggests that the role of ROBO2 downregulation is in drug-resistance development." (PMID 35628654, 2022). "Basal SLIT2, SLIT3, ROBO1, ROBO2 and ROBO4 expression was lower in primary cultures of ovarian cancer epithelial cells when compared to normal OSE (P<0.05) and in poorly differentiated SKOV-3 cells compared to the more differentiated PEO-14 cells (P<0.05)." (PMID 22132142, 2011).
autism spectrum disorder (3 papers, 2016 to 2024). A spectrum of developmental disorders that includes autism, and Asperger syndrome. "Notably, OXT, Robo2 and Slit3 have all been implicated in Autism spectrum disorders." (PMID 31180321, 2019). "Moreover, intronic deletions in ROBO2 have been found in two independent cases with autism-spectrum disorders." (PMID 26877820, 2016).
breast carcinoma (3 papers, 2008 to 2018). "In terms of oncogenes, ROBO2 (roundabout, axon guidance receptor, 2), a receptor of the SLIT2 axon guidance and cell migration growth factor, is associated with poor prognosis of breast cancer." (PMID 20015385, 2009). "CXCL12 was reported to activate the migration of human melanoma and breast cancer cells that express CXCR4, ROBO1 and ROBO2, while SLIT2-ROBO interaction was demonstrated to inhibit chemotaxis, chemoinvasion and adhesion of breast cancer cells." (PMID 19114000, 2008).
cyst (3 papers, 2014 to 2021). A sac-like closed membranous structure that may be empty or contain fluid or amorphous material. "In contrast, defects produced by Robo2 loss of function in cyst stem cells of the Drosophila testis can be rescued by overexpression of ECad indicating that the nature of the regulation depends on the cellular context." (PMID 33968921, 2021). "Together, these data suggest that Slit locally activates Robo2 in adjacent germline and/or cyst stem cells." (PMID 25375180, 2014). "Robo-null CySC clones are lost too rapidly to be detected at 2 days ACI, showing that like Robo2, Robo is required for cyst cell maintenance." (PMID 25375180, 2014). "Interestingly, expression of Robo2 requires JAK-STAT signaling, an important maintenance pathway for both germline and cyst stem cells in the testis." (PMID 25375180, 2014). "However, ectopic Robo2 expression in CySCs and cyst cells is not sufficient to produce an accumulation of stem cells outside the testis niche." (PMID 25375180, 2014). "However, we cannot rule out the possibility that Robo2 is required for Eya expression since Robo2 protein may persist longer in non-mitotic cyst cells than CySCs, which divide frequently." (PMID 25375180, 2014).
glioma (3 papers, 2023 to 2025). A benign or malignant brain and spinal cord tumor that arises from glial cells (astrocytes, oligodendrocytes, ependymal cells). "This analysis identified novel variants between the roundabout guidance receptor 1 (ROBO1) and receptor 2 (ROBO2) genes that were associated with higher likelihood of being IDHwt (versus IDHmut) among glioma patients that carry the G-allele for rs55705857." (PMID 40709013, 2025). "Conversely, decreased Slit1 along with increased Robo2,4 expression was associated with poor prognosis in the low-grade glioma dataset." (PMID 39456164, 2024). "Moreover, both Robo1 and Robo2 expression were detected in tumor cells, suggesting that Slit2 effects in glioma angiogenesis were mediated through these receptors." (PMID 39456164, 2024). "SLIT2/ROBO2-mediated PI3K-γ activation accelerated microglia/macrophage chemotaxis and tumor-supportive polarization, thus enhancing macrophage invasion and diminishing efficacy of chemotherapy and immunotherapy in gliomas." (PMID 36998443, 2023).
leukemia (3 papers, 2013 to 2019). A malignant (clonal) hematologic disorder, involving hematopoietic stem cells and characterized by the presence of primitive or atypical myeloid or lymphoid cells in the bone marrow and the blood. "In in vitro experiments, overexpression of ROBO1 or ROBO2 produces anti-proliferative and pro-apoptotic effects in leukaemia cells." (PMID 26608094, 2015). "Overexpression of ROBO1 or ROBO2 produces anti-proliferative and pro-apoptotic effects in leukaemia cells in vitro." (PMID 26608094, 2015). "Next, we investigated the effect of the addition of exogenous recombinant hSLIT2 together with the overexpression of ROBO1 or ROBO2 on the biological characteristics of leukaemia cells (magnification effect of SLIT2/ROBO signalling)." (PMID 26608094, 2015). "The results showed that ectopic expression of ROBO1 or ROBO2 produced varying degrees of an anti-tumour effect in leukaemia cells, whereas extracellular ROBO mutants lost this effect." (PMID 26608094, 2015). "The analysis also singled out ROBO2 (deleted in 9% of cases and mutated in 3%) a candidate tumor suppressor in head and neck cancer, and MSR1 (deleted in 22% of cases and mutated in 3%), a gene with tumor suppressor function in leukemia stem cells of chronic myeloid leukemia." (PMID 23531283, 2013). "To further confirm the anti-tumour effect of ROBO1 and ROBO2 in MDS and leukaemia cells, we further performed experimetns in vitro by overexpressing of wild-type and mutant ROBO in leukaemia cells." (PMID 26608094, 2015). "Considering the low expression level of ROBO1 and ROBO2 in leukaemia cell lines, we transfected the ROBO1 and ROBO2 expression vectors into K562 and HEL cell lines using the SuperFect Transfection system to observe the effect of ROBO1 or ROBO2 on the biological characteristics of leukaemia cells." (PMID 26608094, 2015).
lung fibrosis (3 papers, 2019 to 2022). "SLIT2 and ROBO2 have been evidenced to prevent fibrotic processes in several diseases, including pulmonary fibrosis." (PMID 34442380, 2021).